WNT2 (Wnt family member 2)
Diseases named in the same sentence as WNT2 in open-access papers (continued):
Sharing a sentence is not in itself a finding about the gene and the disease.
diabetes (3 papers, 2021 to 2023). "In the gastrocnemius muscle, several genes involved in the Wnt signaling pathway were downregulated by diabetes, including Wnt2, Mpc1, Npnt, and Lrp6, whereas Fzd4 was higher in muscle from D mice." (PMID 38025035, 2023). "In addition, the previous study showed that the protein expression of Wnt2 and β-catenin is upregulated in the left ventricles of streptozotocin (STZ)-induced diabetes mellitus (DM) rats, and blocking the Wnt/β-catenin signaling pathway can put off the development of DCM." (PMID 36237833, 2022).
Dupuytren disease (3 papers, 2016 to 2021). "Based on power calculations and results when excluding participants with comorbid Dupuytren disease, the investigators suggested that WNT2 is more strongly associated with susceptibility to Peyronie's disease than to Dupuytren disease." (PMID 33855203, 2021). "Recently, a genetic locus that PD shares with Dupuytren's contracture was identified; WNT2 is the locus involved in genetic predisposition for both Dupuytren's disease and PD." (PMID 28744308, 2017). "Possibly, a negative feedback mechanism in which the WNT2 gene is being suppressed as a reaction to excessive activation of the Wnt signaling pathway, plays a role in Dupuytren’s disease." (PMID 26635199, 2016).
liver cancer (3 papers, 2019 to 2025). An epithelial or non-epithelial malignant neoplasm that arises from the liver. "Elevated lncRNA-DAW mediated the degradation of EZH2 (a negative regulatory factor of WNT2), and WNT2 activated Wnt/β-catenin pathway after it’s removed inhibition, which promotes the progression of liver cancer." (PMID 39838405, 2025). "LncRNA‐DAW plays a crucial role in liver cancer development by activating the expression of Wnt family member 2 (Wnt2)." (PMID 39690143, 2024). "WNT-2 was upregulated in liver cancer cells cultured in MRC-5-CM." (PMID 31523179, 2019).
liver disease (3 papers, 2022 to 2023). "Concerning genes involved in the development of liver disease, Egfr, Vegfb, Wnt2,Pparg and six other genes were dysregulated in multiple independent datasets." (PMID 35203502, 2022). "Moreover, induction of alcohol-induced liver disease in rats resulted in increased expression of cytosolic and nuclear β-catenin, phosphorylated GSK3β, and significantly increased gene expression of Wnt2, Wnt7a, and β-catenin target genes." (PMID 35663960, 2022).
lung adenocarcinoma (3 papers, 2012 to 2024). A carcinoma that arises from the lung and is characterized by the presence of malignant glandular epithelial cells. "Wnt2 has been shown to promote lung adenocarcinoma and fibroblast proliferation." (PMID 38926362, 2024). "In addition, obviously higher expression of oncogenes c-MYC, WNT1, WNT2, and NOTCH1 was detected in side population (SP) cells than in non-side population (NSP) cells of human lung adenocarcinoma cell line-A549, revealing a possible mechanism for the tenacious tumorigenic potential of CSCs." (PMID 22615765, 2012).
ovarian carcinoma (3 papers, 2015 to 2025). A malignant neoplasm originating from the surface ovarian epithelium. "Several of the analyzed genes (TGFβ-1, IL19, CXCR4, BMP1, VCAN, and WNT2) showed elevated expression across multiple cancer types in pan-cancer datasets, including lung, colon, and ovarian cancers." (PMID 41348904, 2025).
schizophrenia (3 papers, 2010 to 2015). A major psychotic disorder characterized by abnormalities in the perception or expression of reality. "Overall, these results give little support to the existence of a genetic association between Wnt2 and schizophrenia." (PMID 24403877, 2013). "In this study, therefore, we investigated the association between WNT2 polymorphisms and schizophrenia in a Korean population." (PMID 20492734, 2010). "This study aimed to determine whether certain SNPs of WNT2 were associated with schizophrenia in a Korean population." (PMID 20492734, 2010). "Wingless-type MMTV integration site family member 2 (WNT2) has a potentially important role in neuronal development; however, there has yet to be an investigation into the association between single nucleotide polymorphisms (SNPs) of WNT2 and schizophrenia." (PMID 20492734, 2010). "The wingless-type MMTV integration site family, member 2 (WNT2) gene is located at chromosome 7q31.2, a region that, in a genome scan study, showed evidence of a link to schizophrenia." (PMID 20492734, 2010). "e genotyped 7 selected SNPs in the WNT2 gene region (approximately 46 Kb) using direct sequencing in 288 patients with schizophrenia and 305 healthy controls." (PMID 20492734, 2010). "WNT2 SNPs haplotype frequencies in schizophrenia patients and healthy controls." (PMID 20492734, 2010). "There have been no published investigations of the association between WNT2 genetic polymorphisms and schizophrenia, despite its potentially important developmental roles and its importance in genetics." (PMID 20492734, 2010). "We investigated possible associations between WNT2 gene SNPs and schizophrenia, and the results were negative." (PMID 20492734, 2010). "In addition, we investigated the LD between the WNT2 SNPs and performed a haplotype analysis between the schizophrenia and control subjects." (PMID 20492734, 2010). "We could not find any association between WNT2 and schizophrenia, indicating that there is no genetic association between WNT2 and schizophrenia." (PMID 20492734, 2010). "The WNT2 gene is located at chromosome 7q31.2; the 7q31 region showed in the Genome Scan of European-American Schizophrenia Pedigrees a significant linkage to schizophrenia, but this is not a sufficiently strong point for the involvement of Wnt2 in schizophrenia." (PMID 24403877, 2013). "The present study does not support a major role for WNT2 in schizophrenia." (PMID 20492734, 2010). "For that reason, it appears the SNPs of WNT2 may not influence the development of schizophrenia in the Korean population, but, still, additional genetic studies will help develop understanding of the precise mechanisms underlying pathogenesis in schizophrenic patients." (PMID 20492734, 2010). "The results suggest that WNT2 may not be involved in the pathogenesis of schizophrenia." (PMID 20492734, 2010).
adenoma (2 papers, 2017 to 2021). A neoplasm arising from the epithelium. "In the intestinal tumors, WNT2 expression was abundant in the adenomas and carcinomas of the deletion carriers, but not detected in SI-NET tissue." (PMID 34274970, 2021).
attention deficit-hyperactivity disorder (2 papers, 2015 to 2024). A disorder characterized by a marked pattern of inattention and/or hyperactivity-impulsivity that is inconsistent with developmental level and clearly interferes with functioning in at least two settings (e.g. at home and at school). "Impairment in the Wnt pathway has been associated with various psychiatric disorders in humans, such as WNT1, WNT2, and WNT7A in autism spectrum disorder, WNT7B and LRP5 in SCZ, and LRP5 and LRP6 in attention-deficit/hyperactivity disorder." (PMID 39452096, 2024).
breast tumor (2 papers, 2018 to 2025). "Boxplot representation of Wnt2 (A) (Student’s t test, P < 2.2 × 10− 16) and Fzd9 (Frizzled9) (B) (Student’s t test, P < 2.2 × 10− 16) in human breast tumors with low (IGF-1R z-score < − 1) versus high (IGF-1R z score > 1) IGF-1R expression." (PMID 30458886, 2018). "Similarly, WNT2 and WNT7B were highly upregulated, whereas WNT11 was highly downregulated in HER2-positive breast tumors compared with that in the control tissue." (PMID 41044153, 2025).
chronic myeloid leukemia (2 papers, 2019 to 2021). "MiRNA-199a/b-5p promoted imatinib efficacy through inhibiting the Wnt2 signaling pathway-mediated protective autophagy in imatinib-resistant chronic myeloid leukemia cells." (PMID 33927285, 2021). "It is reported that miR-199a/b-5p enhances imatinib efficacy via repressing WNT2 signaling-mediated protective autophagy in imatinib-resistant chronic myeloid leukemia cells." (PMID 31636666, 2019).
craniosynostosis (2 papers, 2011 to 2017). Craniosynostosis is defined as the premature fusion of one or more cranial sutures leading to secondary distortion of skull shape resulting in skull deformities with a variable presentation. "Also, a recent microarray study comparing osteoblast expression from wild-type and Apert syndrome fetuses identified concurrent WNT2 and SFRP1 upregulation in the tissues derived from syndromic craniosynostosis cases." (PMID 22028906, 2011). "Consequently, we demonstrated that the accelerated bone formation in cells from fused sutures associated with craniosynostosis is linked with the stiffness-dependent activation of the MAPK-associated non-canonical WNT pathway through activation of JNK3 and WNT2." (PMID 28904366, 2017).
fibrosis (2 papers, 2014 to 2025). the formation of excess fibrous connective tissue in an organ or tissue in a reparative or reactive process. "Although induction of Lrp6 was less in Ad vectors-induced fibrosis than bleomycin-induced fibrosis, induction of Wnt2, 2b, and 5b was comparable between these two fibrosis models." (PMID 25551570, 2014).
hepatocellular carcinoma (2 papers, 2021 to 2022). A malignant tumor that arises from hepatocytes. "Namely, Egfr, Vegfb, Wnt2, and Wnt5b, are all genes that play a role in the development or progression of hepatocellular carcinoma." (PMID 35203502, 2022).
idiopathic pulmonary fibrosis (2 papers, 2012 to 2024). Idiopathic pulmonary fibrosis (IPF) is a nonneoplastic pulmonary disease that is characterized by the formation of scar tissue within the lungs in the absence of any known cause. "Recent studies have implicated Wnt2 and Wnt11 in the progression of cardiac and pulmonary fibrosis." (PMID 38267432, 2024). "Studies in animal models, as well as in human disease, have identified several components of the canonical WNT signaling pathway, including WNT2, FZD7, LRP6, β-CATENIN and GSK-3β which are overexpressed in idiopathic pulmonary fibrosis (IPF)." (PMID 22846383, 2012).
iron deficiency (2 papers, 2025 to 2026). "In addition to iron deficiency anemia tests, immunohistochemical markers such as SCL11a, IRE1, Wnt2, and CD71 were examined." (PMID 40218909, 2025).
ischemia (2 papers, 2022 to 2025). A hypoperfusion of the BLOOD through an organ or tissue caused by a PATHOLOGIC CONSTRICTION or obstruction of its BLOOD VESSELS, or an absence of BLOOD CIRCULATION. "Due to the short duration of ischemia, we delivered rbWnt2 into the mice before ischemia and observed the cardioprotection of Wnt2 following I/R." (PMID 41397965, 2025). "Nevertheless, the worsen of forelimb activity by Wnt2 knockdown suggested that astrocytic dedifferentiation was beneficial for functional recovery following ischemia." (PMID 36056026, 2022). "To evaluate the functional significance of astrocyte dedifferentiation, we analyzed forelimb activity of control shRNA treated mice and Wnt2 shRNA treated mice following focal ischemia in the forelimb sensorimotor cortex by cylinder test." (PMID 36056026, 2022). "To test whether Wnt2 was involved in the acquisition of dedifferentiated phenotype of reactive astrocytes in vivo, we made focal ischemia in bilateral cortices, injected lentivirus expressing Wnt2 shRNA in the right cortex and lentivirus expressing control shRNA in the left cortex." (PMID 36056026, 2022).
metastatic disease (2 papers, 2018 to 2025). "We looked at the TGFβ-1, CXCR4, BMP1, VCAN, and WNT2 expression profiles in a few BC datasets related to primary and metastatic tumors." (PMID 41348904, 2025). "TGFβ-1, CXCR4, BMP1, VCAN, and WNT2 are more expressed in original tumors compared to metastatic tumors, according to the data." (PMID 41348904, 2025).
osteosarcoma (2 papers, 2017 to 2020). A usually aggressive malignant bone-forming mesenchymal neoplasm, predominantly affecting adolescents and young adults. "When compared to adjacent non-cancerous tissues, the expression of Wnt2 protein was elevated in human osteosarcoma tissues." (PMID 32711579, 2020).
Peyronie disease (2 papers, 2016 to 2021). A condition characterized by hardening of the penis due to the formation of fibrous plaques on the dorsolateral aspect of the penis, usually involving the membrane (tunica albuginea) surrounding the erectile tissue (corpus cavernosum penis). "A significant association was observed with WNT2 (P = .002; after Bonferroni correction), which is believed to protect against development of Peyronie's disease." (PMID 33855203, 2021). "In this context, it is of interest to note that WNT2 was also found to be a susceptibility locus in the related Peyronie’s disease, in which the penis is affected." (PMID 26635199, 2016).
Salmonella Infections (2 papers, 2019 to 2022). Infections with bacteria of the genus SALMONELLA. "Based on the previous studies on Wnt protein, we hypothesize that the upregulation of LINC00152 is the host reaction to defense against Salmonella infection and inhibit enteric bacterial-induced inflammation, similar to the role of upregulation of wnt2 and wnt1 in response to Salmonella infection." (PMID 35959377, 2022).
squamous cell carcinoma (2 papers, 2014 to 2025). A carcinoma arising from squamous epithelial cells. "Since the signaling pathways mediated by STAT3, Notch1 and Wnt2 play beneficial roles in CC formation and progression, the effects of resveratrol on them in cervical adenocarcinoma (HeLa) and squamous cell carcinoma (SiHa) cells were analyzed." (PMID 25061499, 2014).
Strabismus (2 papers, 2017 to 2024). A misalignment of the eyes so that the visual axes deviate from bifoveal fixation. "In our previous study of linkage analyses, we have reached two potential candidate genes for strabismus susceptibility, MGST2 and WNT2 in chromosomal loci 4q28.3 and 7q31.2, respectively." (PMID 39000095, 2024). "This study with different analytical methods for genetic statistics provides evidence that MGST2 and WNT2 are potential candidate genes for comitant strabismus in Japanese population." (PMID 29062608, 2017). "This study suggests that MGST2 and WNT2 are potential candidates for comitant strabismus in Japanese population." (PMID 29062608, 2017). "Both MGST2 and WNT2 are known to be expressed in the brain (Jakobsson, Mancini & Ford-Hutchinson, 1996; Cadigan & Nusse, 1997) and likely to be involved in the development of comitant strabismus." (PMID 29062608, 2017).
Stroke (2 papers, 2020 to 2022). Sudden impairment of blood flow to a part of the brain due to occlusion or rupture of an artery to the brain. "In this study, the protein expression of IL-17 was downregulated by either giving As IV or knocking out IL-17, while the protein expression of Wnt2 and Nestin in the ipsilateral hippocampus was upregulated by knocking out IL-17 after stroke in vivo, by western blotting." (PMID 32317974, 2020). "Targeting Wnt2 5UTR or DAP5 may shed insight on developing new treatment for stroke." (PMID 36056026, 2022).
Alzheimer disease (1 paper, 2025). A progressive, neurodegenerative disease characterized by loss of function and death of nerve cells in several areas of the brain leading to loss of cognitive function such as memory and language. "For the advanced age group, the top abundant proteins included cell signaling glycoprotein Wnt-2 (WNT2), which is associated with testicular morphology and sperm motility and neurodegenerative diseases such as Alzheimer’s disease." (PMID 40649876, 2025).
Anxiety (1 paper, 2016). Intense feelings of nervousness, tension, or panic often arise in response to interpersonal stresses. "We also investigated the role of Wnt2 and Wnt3 in anxiety-like behaviors." (PMID 27622936, 2016).
astrocytoma (1 paper, 2010). "In astrocytoma, the level of Wnt-2, Wnt-5a and β-catenin protein is strikingly increased compared with normal brain tissue." (PMID 20334650, 2010).
atrial septal defect (1 paper, 2017). Interauricular communication is a congenital malformation characterized by a communication between the atrial chambers of the heart. "It was previously found that Wnt2 and Gata6 act in the same genetic pathway in the posterior SHF during heart development and when inactivated cause atrial septal defects among other anomalies." (PMID 28346476, 2017).
bone sarcoma (1 paper, 2015). A sarcoma that arises from the bone. "In this study, we found that five of six canonical Wnt ligands (Wnt1, 3, 3a, 8b and 10b) in bone sarcoma cells were prominently increased, while Wnt2 expression was remarkably decreased." (PMID 25999350, 2015).
cardiomyopathy (1 paper, 2025). A disease of the heart muscle or myocardium proper. "In conclusion, this work redefines Wnt2 as a master regulator of I/R injury through Nap1L1-mediated transcriptional reprogramming, providing a mechanistic foundation for targeting redox dysregulation and multiple forms of cell death in post-I/R cardiomyopathy." (PMID 41397965, 2025).
cervical tumor (1 paper, 2016). "We found that expression of WNT2 was evaluated in cervical tumor samples, especially in samples with PLNM." (PMID 27513465, 2016). "Moreover, downregulation of WNT2 could inhibit cervical tumor cell motility and invasion, and reversed EMT by inhibiting the WNT2/β-catenin pathway." (PMID 27513465, 2016).
colorectal adenocarcinoma (1 paper, 2019). The most common type of colorectal carcinoma. "We then conducted immunohistochemical analysis on Wnt2 in 171 patients who had undergone colorectal adenocarcinoma surgery." (PMID 31468733, 2019). "Thus, we performed immunohistochemical analysis on Wnt2 in 171 patients who underwent surgery for colorectal adenocarcinoma." (PMID 31468733, 2019).
cystic fibrosis (1 paper, 2021). Autosomal recessive disorder caused by pathogenic variants in the CFTR gene (cystic fibrosis transmembrane conductance regulator), which encodes a chloride and bicarbonate channel expressed in epithelial cells, and follow the diagnosis criteria. "Whether the vicinity of WNT2 locus contributes to intestinal cancer predisposition in cystic fibrosis mutation carriers remains to be examined." (PMID 34274970, 2021).
Duchenne muscular dystrophy (1 paper, 2024). Duchenne muscular dystrophy (DMD) is a neuromuscular disease characterized by rapidly progressive muscle weakness and wasting due to degeneration of skeletal, smooth and cardiac muscle. "Among this cohort of miRNAs, studies have illuminated the role of miR-199a-5p in Duchenne muscular dystrophy (DMD), where it influences the WNT signaling pathway via genes such as FZD4, JAG1, and WNT2, thereby impacting cellular proliferation and myogenic differentiation." (PMID 38600177, 2024).
endometriosis (1 paper, 2022). The growth of functional endometrial tissue in anatomic sites outside the uterine body. "The communication via Wnt2/β-catenin signalling in endometriosis was assessed." (PMID 35158846, 2022). "In endometriosis, metformin might modify the stroma–epithelium communication via Wnt2/β-catenin." (PMID 35158846, 2022).
epilepsy (1 paper, 2022). A brain disorder characterized by episodes of abnormally increased neuronal discharge resulting in transient episodes of sensory or motor neurological dysfunction, or psychic dysfunction. "Similarly, using an electroconvulsive epilepsy model, increased expression of Wnt2 and beta-catenin was observed in the hippocampal subgranular zone during the first 48 h after seizure induction, supporting our observation that canonical Wnt signaling is upregulated in early epileptogenesis." (PMID 36233336, 2022).
focal cortical dysplasia type II (1 paper, 2023). "For example, after a germline pathogenic truncation variant in NPRL3 was identified in a patient with focal cortical dysplasia type II (FCORD2; OMIM: #607341), a somatic missense variant in the WNT2 gene in brain-derived DNA was detected." (PMID 36672937, 2023).